GSDMD (gasdermin D)
Diseases named in the same sentence as GSDMD in open-access papers (continued):
Sharing a sentence is not in itself a finding about the gene and the disease.
autoimmune disease (15 papers, 2020 to 2025). A disorder resulting from loss of function or tissue destruction of an organ or multiple organs, arising from humoral or cellular immune responses of the individual to their own tissue constituents. "Furthermore, GSDMD can be activated by cleaved caspase-11 and perforate the nuclear membrane, causing the leakage of DNA and promoting the formation of neutrophil extracellular traps, which has been validated in many autoimmune diseases." (PMID 36217543, 2022). "GSDMD encodes a member of the adermin family of pore-forming proteins implicated in the immune response, which controls the release of the proinflammatory cytokines IL-1ß, IL-18 and pyroptotic cell death, and drive the inflammation in septic shock as well as the autoimmune diseases." (PMID 33255903, 2020). "Several studies have shown that suppressing the production of NETs by inhibiting the functions of PAD4 and/or GSDMD provides therapeutic or protective effects in autoimmune diseases, suggesting that PAD4 and GSDMD can serve as potential therapeutic targets." (PMID 39935468, 2025). "GSDMD plays a crucial role in the progression of several autoimmune diseases by mediating pyroptosis and amplifying inflammatory responses." (PMID 39994107, 2025). "In infectious and autoimmune diseases, despite variations in activating factors, GSDMD predominantly regulates immune cell activity, resulting in inflammatory dysregulation and promoting disease progression." (PMID 39994107, 2025). "Gasdermin D (GSDMD) is emerging as an important player in autoimmune diseases, but its exact role in lupus nephritis (LN) remains controversial." (PMID 38831451, 2024). "GSDMD also functions as the shared common effector of multiple inflammasomes that actively involved in a body of inflammatory and autoimmune diseases." (PMID 35774778, 2022). "Conceivably, GSDMD acts as the crucial executor of pyroptosis and plays a significant role in various diseases, including autoimmune diseases, infectious inflammatory diseases, and other pyroptosis-associated diseases." (PMID 35774778, 2022). "Moreover, we examine the interactive feedback mechanisms among NLRP3 inflammasome, S100A8/A9, and Gasdermin D, exploring their implications in autoimmune diseases." (PMID 40948742, 2025). "The selective inhibitors of GSDMD, inflammasomes, and caspase-1 are identified to ameliorate inflammation and thrombosis, and some of them exhibit excellent therapeutic efficacy in several autoimmune diseases." (PMID 37063905, 2023). "Emerging insight highlights the role of GSDMD-mediated pyroptosis in autoimmune diseases." (PMID 36967609, 2023). "GSDMD activation and inhibition have different effects on autoimmune diseases." (PMID 36967609, 2023). "Gasdermin D (GSDMD), the pore-forming effector protein, is involved in diverse inflammatory and autoimmune diseases." (PMID 38831451, 2024). "Gasdermin D (GSDMD) serves as a key executor to trigger pyroptosis and is emerging as an attractive checkpoint in host defense, inflammatory, autoimmune diseases, and many other systemic diseases." (PMID 35774778, 2022). "GSDMD is broadly expressed and plays a pivotal regulatory role in non-tumor diseases, which can be categorized into infectious, non-infectious, and autoimmune diseases." (PMID 39994107, 2025). "GSDMD expression is significantly upregulated in non-tumor diseases (non-infectious, infectious and autoimmune diseases) and significantly change in tumor diseases." (PMID 39994107, 2025).
Cognitive impairment (15 papers, 2019 to 2026). Abnormal cognition is characterized by deficits in thinking, reasoning, or remembering. "In a homocysteine-induced cognitive impairment model, an independent risk factor for AD, betaine alleviated cognitive impairment by inhibiting the NLRP3/caspase-1/GSDMD pathway in an m6A-YTHDF2-dependent manner, thereby suppressing microglial pyroptosis." (PMID 41608511, 2026). "Gasdermin D (GSDMD)-mediated pyroptotic cell death is implicated in the pathogenesis of cognitive deficits in sepsis-associated encephalopathy (SAE), yet the underlying mechanisms remain largely unclear." (PMID 38627764, 2024). "Our data indicate that the GSDMD/Drp1 signaling pathway is involved in cognitive deficits in a mouse model of SAE." (PMID 38627764, 2024). "This study aimed to investigate the potential role of the GSDMD/Drp1 signaling pathway in cognitive impairments in a mouse model of SAE." (PMID 38627764, 2024). "Fourthly, the contributions of NLRP3 and GSDMD to the migraine-related cognitive impairment need to be further investigated using targeted therapeutic compounds." (PMID 35780081, 2022). "It has been proposed that the Caspase-1 inhibitor VX765 suppressed the expression of GSDMD and its cleavage form GSDMD-N, which diminished microglia activation and protein cognitive impairment." (PMID 35401226, 2022). "With this regard, expressions of NLRP3, GSDMD-NT, and cleaved caspase-1 were augmented in the brain of septic mice, and the upregulation of NLRP3, caspase-1, and gasdermin-D in the hippocampus resulted in the cognitive deficits in the mice model of SAE by inducing pyroptosis." (PMID 35832175, 2022). "We and others have recently demonstrated that the GSDMD-induced pyroptosis is involved in cognitive impairment induced by the volatile anesthetic isoflurane in aged mice and in hippocampal neurotoxicity induced by the intravenous anesthetic ketamine in mouse primary hippocampal neurons." (PMID 34419096, 2021). "Thus, inhibition of GSDMD pore formation appears to be another protective effect of BAY 11-7082 against GA-induced cognitive deficits." (PMID 34419096, 2021). "Importantly, inhibiting the GSDMD/Drp1 pathway effectively reverses neuronal injury, synaptic damage, and abnormalities in neural oscillations in the hippocampus of septic mice, thereby improving cognitive deficits." (PMID 38627764, 2024). "Therefore, in the present study, we set out to investigate whether GSDMD-induced pyroptosis mediated by inflammatory caspases might be involved in the pathophysiology of neuroinflammation and cognitive deficits after repeated neonatal sevoflurane exposure in developing rats." (PMID 34419096, 2021). "The role of GSDMD and GSDME-mediated pyroptosis in cognitive impairment have been elucidated, but the mechanisms of other gasdermin family members such as GSDMA, GSDMB, GSDMC and DFNB59 in cognitive impairment remained unclear." (PMID 37332874, 2023). "GSDMD-NT, acting as a secretion pathway for inflammatory factors, participates in CIH-induced cognitive impairment through a non-pyroptotic mechanism." (PMID 39595526, 2024).
colon cancer (15 papers, 2019 to 2025). "Structured illumination microscopy (SIM) imaging revealed low expression of GSDMD-NT in colon cancer cells." (PMID 40963981, 2025). "Allogeneic transfusion of an aggressive dose fresh neutrophils with precise navigation can stimulate neutrophil infiltration within the tumor microenvironment and induce multimodal death in colon cancer cells by generating NETs and releasing GSDMD-NT and NE." (PMID 40963981, 2025). "GSDMD-NT forms pores on the plasma membrane of colon cancer cells, enabling NE (released with NETs) to enter the colon cancer cells and even penetrate into the nucleus, damaging and lysing the cells." (PMID 40963981, 2025). "We probed for the full-length GSDMD and N’-GSDMD protein both in normal colon and colonic tumors, and confirmed the whole-body ablation of Gsdmd in sporadic CRC mice." (PMID 38898209, 2024). "Our in vitro and in vivo results indicated that simvastatin induced pyroptosis through ROS/caspase-1/GSDMD pathway, thereby serving as a potential agent for colon cancer treatment." (PMID 37974278, 2023). "In conclusion, we have revealed that simvastatin induces pyroptosis through ROS/NLRP3/caspase-1/GSDMD pathway in colon cancer." (PMID 37974278, 2023). "Western blotting analysis showed that luteolin treatment increased the expression of Caspase1, Gasdermin D and IL-1β, which are members of the pyroptosis signalling pathway, in colon cancer cells." (PMID 36105214, 2022). "They confirmed synergism of cytokines TNF-α and IFN-γ was capable of inducing PANoptosis of colon cancer cells through activation of GSDMD, GSDME, caspase-8, caspase-3, caspase-7 and MLKL, thereby suppressing tumor growth." (PMID 36505474, 2022). "In colon cancer, simvastatin induced pyroptosis via the caspase-1/GSDMD pathway." (PMID 40756987, 2025). "Similarly, quercetin promotes gasdermin D (GSDMD)-mediated pyroptosis in colon cancer cells by upregulating NEK7, enhancing NLRP3 inflammasome assembly, and GSDMD cleavage." (PMID 40225345, 2025). "Thioredoxin reductase 3 (Txnrd3) as selenoprotein was recently proved to cause intracellular calcium outflow and increase oxidative stress in colonic epithelial cell line, thereby activating the canonical GSDMD-dependent pyroptosis to inhibit the growth and proliferation of colon cancer cells." (PMID 36505474, 2022). "Interestingly, it was reported that conjugated linolenic acid produced by the probiotic bacterium Lactobacillus exerted the anti-cancer effect through inducing GSDMD-mediated pyroptosis of colon cancer cells." (PMID 36505474, 2022). "Our results show that gut microbiota/NLRP3-mediated activation of GSDMD promotes the development of colorectal tumors, and supports the use of NLRP3 inhibitors to treat colon cancer." (PMID 38898209, 2024). "Ablation of GSDMD in hematopoietic cells also did not impact the development of early-stage colon tumors." (PMID 38898209, 2024). "GSDME, rather than GSDMD, was demonstrated to be cleaved in lobaplatin-induced pyroptosis in colon cancer cells due to caspase-3 activation, which clarified the mechanism of lobaplatin eradicating neoplastic cells." (PMID 36505474, 2022). "In summary, these data indicated that GSDME rather than GSDMD is cleaved in lobaplatin-induced pyroptosis in colon cancer cells and that the cleavage of GSDME is due to caspase-3 activation." (PMID 30804337, 2019). "In addition, ablation of GSDMD in the mouse model of sporadic colon cancer also did not alter the frequency of Th17 cells or regulatory T cells (Tregs)." (PMID 38898209, 2024). "However, ablation of GSDMD in sporadic colon tumors did not result in altered IL-1α, IL-1β, and IL-18 as well as NLRP3 or ASC speck formation." (PMID 38898209, 2024). "This demonstrates that CVB3 induces pyroptosis of colon cancer cell lines through the casp-3/GSDME pathway and not the GSDMD pathway." (PMID 36551691, 2022).
colon cancer (continued). "First, in human colon cancer cell lines (SW480 and HT-29) that naturally expressed GSDMD but no other gasdermins, AE only triggered apoptotic cell death (yellow arrows)." (PMID 35662735, 2022).
renal fibrosis (15 papers, 2020 to 2026). A final common manifestation of a wide variety of chronic kidney diseases characterized by glomerulosclerosis and tubulointerstitial fibrosis. "Another study has shown that deficiency of GSDMD ameliorated the folic acid‐induced renal fibrosis and the GSDMD‐dependent neutrophil extracellular traps formation promoted macrophage‐to‐myofibroblast transition." (PMID 39320020, 2024). "In this study, we observed that Caspase-11/GSDMD activation was associated with renal fibrosis, inflammatory cell infiltration, proinflammatory and profibrogenic factors expression, and α-SMA production." (PMID 38436813, 2024). "Our experiments using AAV9 to knockdown GSDMD in DKD mice significantly alleviated renal fibrosis and inflammation, underscoring the pivotal role of pyroptosis in these pathological processes." (PMID 40462493, 2025). "Our previous study demonstrated that both Caspase-11 and GSDMD were activated and contributed to renal fibrosis in obstructed kidneys." (PMID 38436813, 2024). "Altogether, these findings provide the compelling evidence that Caspase-11/GSDMD in hematopoietic cells is responsible for the progression of renal fibrosis in hyperuricemic nephropathy." (PMID 38436813, 2024). "In a rat model of unilateral ureteral obstruction, disulfiram pretreatment significantly inhibited pyroptosis via the inhibition of GSDMD cleavage and was able to prevent the development of renal fibrosis." (PMID 36978391, 2023). "Collectively, our findings demonstrate that caspase-11/GSDMD-dependent NETs promote renal fibrosis by facilitating inflammation and MMT, therefore highlighting the role and mechanisms of NETs in renal fibrosis." (PMID 35941120, 2022). "In obstructive nephropathy, GSDMD-dependent neutrophil extracellular traps could accelerate renal fibrosis through macrophage-to-myofibroblast transition." (PMID 37359552, 2023). "Western blot analysis showed increased expressions of ALPK1, phospho-NF-κB P65, GSDMD-NT, and IL-1β in renal tissues of DN mice and HK-2 cells, accompanied with increased renal fibrosis-related proteins (FN, α-SMA) and macrophages infiltration in interstitial areas." (PMID 36732854, 2023). "Therefore, we reveal the involvement of GSDMD-mediated cellular processes in bone marrow-derived cells, not in renal parenchymal cells, in ureteral obstruction-induced renal fibrosis." (PMID 35941120, 2022). "Collectively, these results suggest that TGF-beta-mediated NLRP3 inflammasome activation may cause the release of HMGB1 and an increase in Gasdermin D cleavage in NRK-52E, thereby contributing to renal fibrosis in Ang II-induced CKD." (PMID 32117956, 2020). "Furthermore, MCC950, an NLRP3 inflammasome inhibitor, ameliorated podocyte injury, renal fibrosis, and renal dysfunction in db/db mice, and gasdermin D (GSDMD) knockdown using small interfering RNA (siRNA) in podocytes reversed hyperglycemia-induced inflammation and cell death." (PMID 37373116, 2023). "In addition, we demonstrated that caspase-11, that could cleave GSDMD, was required for NETs formation and renal fibrosis after UUO." (PMID 35941120, 2022). "Our prior investigation established that Caspase-11/GSDMD actively participates in the generation of NETs, which promotes MMT and contributes to renal fibrosis." (PMID 38436813, 2024). "Chimera studies between Gsdmd−/− and Gsdmd+/+ mice identified that GSDMD from bone marrow-derived cells instead of renal parenchymal cells was involved in renal fibrosis." (PMID 35941120, 2022). "Of note, GSDMD deletion reduced inflammatory cell infiltration in the kidneys and suppressed extracellular traps, macrophage-to-myofibroblast transition (MMT), and fibrosis formation, revealing the crucial regulatory effect of GSDMD on renal fibrosis." (PMID 37500614, 2023).
renal fibrosis (continued). "In conclusion, we found that UUO-induced Casp11/GSDMD-dependent NETs formation in neutrophils activated p65 translocation to the nucleus and then stimulated TNF-α and TGF-β1 production in macrophages, which promoted MMT contributing to renal fibrosis." (PMID 35941120, 2022). "Taken together, these data provide evidence that GSDMD activation in neutrophils rather than in macrophages contributes to the progression of renal fibrosis after ureteral obstruction." (PMID 35941120, 2022). "To explore the mechanism by which macrophage pyroptosis induces renal fibrosis, we divided macrophages into two groups: the GSDMD-negative and the GSDMD-positive groups, and analyzed them by scRNA-seq." (PMID 35641484, 2022). "Therefore, our findings show that Casp11/GSDMD-dependent NETs promote inflammation and MMT leading to renal fibrosis in obstructive nephropathy." (PMID 35941120, 2022). "In our current study, we identified Caspase-11/GSDMD as a critical role in progressive hyperuricemic nephropathy, as its deletion significantly reduced the infiltration of neutrophils and macrophages, NETs formation, α-SMA expression in macrophages, and renal fibrosis." (PMID 38436813, 2024).
acute pancreatitis (14 papers, 2020 to 2025). An acute inflammatory process that leads to necrosis of the pancreatic parenchyma. "The functional relevance and effects of the pyroptosis executioner gasdermin D (GSDMD) on severe acute pancreatitis (SAP)-associated lung injury are unclear." (PMID 34858995, 2021). "Furthermore, USP25 is significantly upregulated in acute pancreatitis models and is implicated in the activation of GSDMD-mediated pyroptotic cell death in acinar cells during acute pancreatitis." (PMID 40307577, 2025). "Studies have found that emodin can reduce the increased expression of NLRP3, ASC, caspase-1 p10, and GSDMD proteins in alveolar macrophages induced by acute pancreatitis and improve pancreatitis-associated lung injury by inhibiting macrophage pyroptosis pathway." (PMID 38671352, 2024). "Consistent with other findings, we similarly observed that the cleavage of GSDMD was promoted under acute pancreatitis." (PMID 35721108, 2022). "To conclude, our findings indicate that GSDMD‐mediated pyroptosis is a viable therapeutic target in mice with severe acute pancreatitis (SAP), and disulfiram could potentially provide protective effects against SAP‐associated multiple organ failure (MOF)." (PMID 40801277, 2025). "Disulfiram effectively suppressed the cleavage of GSDMD, ameliorated the development of caerulein‐induced severe acute pancreatitis (SAP) and the corresponding lung injury, and notably attenuated the expression levels of the pro‐inflammatory cytokines IL‐1β and IL‐18." (PMID 40801277, 2025). "Similarly, the expression levels of other pyroptosis activation-associated proteins ASC, GSDMD, and NLRP3 were significantly higher in the acute pancreatitis model." (PMID 38538578, 2024). "However, GSDMD can promote the secretion of inflammatory cytokines by macrophages and aggravate pancreatic histological injury by expanding inflammatory response, which demonstrates two contrasting roles of GSDMD in acute pancreatitis." (PMID 40439590, 2025). "To illustrate, the initiation of pyroptosis and systemic inflammation in acute pancreatitis is facilitated through the activation of acinar cell NLRP3 inflammasome and GSDMD." (PMID 40801277, 2025). "To determine whether pyroptosis is responsible for STC-induced acute pancreatitis, we detected NLRP3 (inflammasome sensor), caspase-1, and GSDMD expression by Western blotting in vivo and in vitro." (PMID 34422214, 2021). "However, the role of GSDMD in acute pancreatitis (AP) is not yet fully elucidated." (PMID 40439590, 2025).